IFI35 (interferon induced protein 35)
Diseases named in the same sentence as IFI35 in open-access papers (continued):
Sharing a sentence is not in itself a finding about the gene and the disease.
colon cancer (1 paper, 2023). "In mice inoculated with shIFI35 cells, IFI35 knockdown significantly promoted tumor growth measured by tumor volume and weight in both murine colon cancer models." (PMID 37380972, 2023). "Then we constructed murine colon cancer cells over-expressing IFI35 and tested their effect on anti-tumor immunity in both immunodeficient and immunocompetent mouse models." (PMID 37380972, 2023). "In murine colon cancer cells challenged with IFNγ, both qPCR and WB analysis revealed increased expression of IFI35." (PMID 37380972, 2023). "Enzyme-Linked Immunosorbent Assay (ELISA) result showed that the level of IFI35 was significantly higher in the supernatant of IFI35-overexpressing cells, and lower in the sh-IFI35 cells, compared to control cells in both murine colon cancer cell models." (PMID 37380972, 2023). "Upon fludarabine treatment, decreased STAT1 mRNA levels in both murine colon cancer cells were observed, and more importantly, the stimulated expression of IFI35 by IFNγ was attenuated." (PMID 37380972, 2023). "Next, CD8+ T cells were treated with the supernatants from both murine colon cancer cells expressing shRNA against IFI35 (shIFI35) and scrambled sequence control (shRNA), respectively." (PMID 37380972, 2023). "Our data have demonstrated that IFNγ enhanced IRF3/7 expression and upregulation of IRF7 increases the expression of IFI35 in both murine colon cancer cells." (PMID 37380972, 2023). "Thus, IRF7 was a unique transcription factor that was stimulated by IFNγ and drove the expression of IFI35 in both murine colon cancer cell lines." (PMID 37380972, 2023). "Importantly, the overexpression of IRF7 significantly increased the expression of IFI35 in both murine colon cancer cell lines." (PMID 37380972, 2023). "Because IFI35 can be released by activated macrophages, we hypothesized that IFI35 is secreted by colon cancer cells to influence nearby CD8+ T cells." (PMID 37380972, 2023). "Additionally, using proteomic analysis from a previous study that employed LC–MS/MS and tandem mass tagging, we investigated IFI35 protein expression levels, and our findings showed that IFI35 was significantly upregulated in normal colon tissues compared to colon cancer tissues." (PMID 37380972, 2023). "On the other hand, with nude mice inoculated with CT26 cells overexpressing IFI35, similar rates of tumor growth were observed compared with nude mice bearing control CT26 colon tumor cells." (PMID 37380972, 2023). "We then injected murine CT26 and MC38 colon cancer cells into syngeneic immunocompetent BALB/C and C57BL/6 mice subcutaneously to investigate the role of IFI35 in antitumor immunity." (PMID 37380972, 2023). "We found that IFI35 was induced by IFNγ at both RNA and protein levels but not affected by LPS, poly IC, and poly A:D in murine colon cancer cells." (PMID 37380972, 2023). "To test this hypothesis, we performed IFI35 knock-down study using a short hairpin RNA against IFI35, and IFI35 over expression study with an IFI35 expression plasmid in murine CT26 and MC38 colon cancer cells." (PMID 37380972, 2023).
cutaneous T-cell lymphoma (1 paper, 2023). "With cutaneous T-cell lymphoma, IFI35 was shown to be significantly down-regulated in the malignant cell population, which is consistent with our finding that IFI35 may suppress tumor growth." (PMID 37380972, 2023).
MELAS (1 paper, 2023). "In IRF2 targets, which were significantly enriched in MELAS subjects, Polg mice, and Tfam± MEFs, USP18, TAP1, BST2, IFI35 were consistently increased." (PMID 37208779, 2023).
rectal cancer (1 paper, 2025). A primary or metastatic malignant neoplasm that affects the rectum. "In rectal cancer cell experiments, the upregulation of IFI35 after X-ray exposure significantly suppressed CRC cell proliferation and colony formation." (PMID 40463715, 2025).
renal carcinoma (1 paper, 2022). A carcinoma arising from the epithelium of the renal parenchyma or the renal pelvis. "In human cell lines, the knockdown of IFI35 suppressed the malignant behavior of renal cancer cells." (PMID 35740527, 2022). "Reducing IFI35 expression by shRNA, suppressed the tumor growth of renal cancer, by enhancing autophagy induction, suggesting that knockdown of IFI35 provided a protective role against renal cancer." (PMID 35740527, 2022). "Western blot results demonstrated that IFI35 expression was significantly reduced in IFI35 shRNA-treated Ketr-3 or 786-O cells, indicating that IFI35 expression was effectively suppressed by shRNA in renal cancer cells." (PMID 35740527, 2022). "The autophagy inhibitor 3-MA also abolished the prevention of tumor growth by deleting IFI35 in renal cancer models." (PMID 35740527, 2022). "In treatment with 3-MA inhibitors, the malignant behavior of tumor cells in IFI35-knockdown renal cancer cells was significantly restored." (PMID 35740527, 2022). "In fact, it inhibited proliferation, migration, and invasion of renal cancer cells treated with IFI35 shRNA compared with the control cells." (PMID 35740527, 2022). "The results demonstrated that knockdown of IFI35 could inhibit the proliferation and invasion of renal cancer cells by enhancing the STAT1/STAT6 phosphorylation (pSTAT1/pSTAT6)-dependent autophagy." (PMID 35740527, 2022). "Therefore, the activation of pSTAT1/pSTAT6 by knockdown of IFI35 in renal cancer cells was involved in the induction of autophagy." (PMID 35740527, 2022). "To investigate whether the knockdown of IFI35 regulated tumor progression by autophagy in RCC, we first detected the induction of autophagy in IFI35 shRNA-treated renal cancer cells." (PMID 35740527, 2022). "Furthermore, the role and mechanism of IFI35 in renal cancer were explored by the cell and animal models." (PMID 35740527, 2022). "Additionally, blockade of STAT1/STAT6 phosphorylation (pSTAT1/pSTAT6) abrogated the induced autophagy by IFI35 knockdown in renal cancer cells." (PMID 35740527, 2022). "Likewise, the inhibition ability of cell proliferation and invasion by deleting IFI35 were blocked by 3-MA in renal cancer cells." (PMID 35740527, 2022). "Moreover, the role and mechanism of IFI35-mediated inflammation involved in macroautophagy induction should be further investigated in renal cancer progression." (PMID 35740527, 2022). "IFI35 expression was also detected in renal cancer cells by Western blot." (PMID 35740527, 2022). "In conclusion, the expression and function of IFI35 were investigated in patient specimens, cellular models, and animal models in order to understand the pathogenesis of RCC, and knockdown of IFI35 was investigated as a therapeutic approach to treat renal cancer." (PMID 35740527, 2022). "Knockdown of IFI35 could inhibit the proliferation and invasion of renal cancer cells by enhancing the STAT1/STAT6 phosphorylation (pSTAT1/pSTAT6)-dependent autophagy." (PMID 35740527, 2022). "Likewise, the knockdown of IFI35 also suppressed the tumor growth or lung metastasis of renal cancer by enhancing the induction of autophagy." (PMID 35740527, 2022). "Taken together, these results indicated that IFI35 knockdown could inhibit tumor growth by pSTAT1/pSTAT6-dependent autophagy signaling and thus effectively prevent the aggravation of renal cancer." (PMID 35740527, 2022). "This conception was again confirmed by the knockdown of IFI35 in renal cancer cells." (PMID 35740527, 2022). "However, we found that pSTAT1/pSTAT6 expression shows a significant change in IFI35-deleting renal cancer cells, so the project mainly focuses on the activation of pSTAT1/pSTAT6." (PMID 35740527, 2022). "In order to investigate whether IFI35 regulates the malignant behavior of renal cancer cells by autophagy in RCC, we used an inhibitor 3-MA to block autophagy." (PMID 35740527, 2022).
renal carcinoma (continued). "Taken together, these results indicate that the knockdown of IFI35 could increase the induction of autophagy by the pSTAT1/pSTAT6-dependent pathway in renal cancer cells." (PMID 35740527, 2022). "Therefore, targeting IFI35 may be a therapeutic strategy for renal cancer or autophagy-mediated cancers." (PMID 35740527, 2022). "Therefore, whether IFI35 regulated autophagy-mediating homeostasis of renal cancer cells needs to be further studied." (PMID 35740527, 2022). "Likewise, pSTAT6 expression levels were also elevated in IFI35 shRNA-treated renal cancer cells." (PMID 35740527, 2022). "Notably, pSTAT1 or pSTAT6 inhibitors could remarkably suppress the LC3-II expression and reduced the ratio of LC3-II/LC3-I, implying that IFI35-mediated autophagy was inhibited by the inhibitor in IFI35-deleted renal cancer cells." (PMID 35740527, 2022). "Our results indicated that the knockdown of IFI35 increased the expression of LC3-II and the ratio LC3-II/LC3-I was higher in renal cancer cells." (PMID 35740527, 2022). "Here, IFI35 expression and function were investigated in RCC tissues, renal cancer cells, and animal models." (PMID 35740527, 2022). "Our results showed that the knockdown of IFI35 increased the expression of autophagy-related genes (Beclin-1, LC3-II, and ATG-5) in renal cancer cells." (PMID 35740527, 2022). "Therefore, STAT3 signaling may partially influence IFI35-mediated autophagy in renal cancer cells." (PMID 35740527, 2022). "To detect whether these signaling pathways were required for IFI35-mediated autophagy, we first detected phosphorylated expression levels of STAT1/STAT6 in IFI35 shRNA-treated renal cancer cells." (PMID 35740527, 2022).
renal cell carcinoma (1 paper, 2022). "Our goal is to explore whether IFI35 could be used as tumor marker or a therapeutic target for renal cell cancer (RCC)." (PMID 35740527, 2022). "However, the biological significance and function of IFI35 in renal cell cancer (RCC) is still not well understood." (PMID 35740527, 2022).
infection (18 papers, 2010 to 2025). The state of being infected such as from the introduction of a foreign agent such as serum, vaccine, antigenic substance or organism. "Ifi35-/- mice exhibited decreased weight loss compared to WT animals at 8, 10, and 12 days post infection (dpi) (P < 0.001)." (PMID 29698474, 2018). "Evidence for NMI and IFI35 (in M2) indicates that they function as damage-associated molecular patterns in the extracelluar space, mediating proinflammatory responses to cellular infection and damage through the activation of the nuclear factor-κB in the Toll-like receptor 4 signalling pathway." (PMID 40656995, 2025). "IFI35 (also known as IFP35) has been reported as a proinflammatory factor during cellular infection." (PMID 36557717, 2022). "To investigate the effects of Ifi35 on type I IFN expression in vivo, we quantified the amount of type I IFN in BALF from WT and Ifi35-/- mice after H5N1-VN/PR8 infection using a highly sensitive L929 and EMCV cell bioassay." (PMID 29698474, 2018). "Given that we observed a sustained reduction of IL-12p40 production in Ifi35-/- mice starting on 1 dpi, we sought to ask if the effect of Ifi35 on IL-12p40 production in vivo was specific for H5N1-VN/PR8 infection." (PMID 29698474, 2018). "Next, we characterized the kinetics of immune cell infiltration into the lungs of WT and Ifi35-/- mice following H5N1-VN/PR8 infection." (PMID 29698474, 2018). "Ifi35 has also been reported to interact with various host and viral proteins to modulate infection, innate immune, and inflammatory responses." (PMID 29698474, 2018). "In the IFE cells, infection was associated with the upregulation of interferon regulatory and inducible genes (IRF, IRF9, IFIT5, IFIH1), while a downregulation of IFI35 and IFI6 was observed, potentially indicating a mechanism to prevent excessive immune activation." (PMID 38743760, 2024). "Finally, it is possible that the effects of Ifi35 on type I IFN expression occur at an earlier time point after infection than what we interrogated." (PMID 29698474, 2018). "Finally, our in vivo poly I:C stimulation shows reduced IL-12p40 serum levels at 3 hours post-infection and provides evidence for a role of basally expressed Ifi35 protein." (PMID 29698474, 2018). "We next assessed whether Ifi35 expression in hematopoietic cells was necessary for cellular recruitment to the lung and IL-12p40 induction following infection." (PMID 29698474, 2018). "In contrast, expression of other genes in the IFN signaling pathway (G1p2, Ifi35, Ifit1 and Stat2) were shown to be higher in the infected WT as compared to the infected Ifnar1-/- mice after days 2 and 3 of infection, when the bacterial load was lower in the infected Ifnar1-/- mice." (PMID 26918359, 2016). "Similarly, expression of several genes in the canonical IFN signaling pathway, including Ifng, Jak2, Stat1, Stat2, Socs1, Irf1, Irf9, Tap1, Ifitm1, Psmb8, Ifi35, Gas1 and Fit3 were up-regulated during infection by the mutant strain." (PMID 25201772, 2014). "In our study, WT mice infected with H5N1-VN/PR8 had increased amounts of IL-12p40 and IL-12p80 in BALF following H5N1-VN/PR8 infection compared to Ifi35-/- mice, suggesting that IL-12p80 may contribute to more severe weight loss; a characteristic of IAV disease." (PMID 29698474, 2018). "Of note, we observed that several duck IFN-stimulated genes (ISGs), including IFI35, Mx, ISG15, ZC3HAV1, LGP2, IFITM1, IFITM2, and Viperin, were dramatically upregulated upon DTMUV infection." (PMID 34335626, 2021). "For instance, RNF125, IFI35, NLRC5, USP25, and A20 have been shown to negatively regulate RIG-I-induced antiviral signaling upon pathogen infection." (PMID 33584728, 2020). "To determine if Ifi35 expression affected viral titer after infection, we quantified the virus load in bronchoalveolar lavage fluid (BALF) of Ifi35-/- and WT mice at 1, 2, 3, 5, 8, and 11 dpi with H5N1-VN/PR8." (PMID 29698474, 2018).
infection (continued). "Following infection, however, the BAL of Ifi35-/- mice contained fewer cells at 2 and 3 dpi (P < 0.01), but not at 1, 5, 8, or 11 dpi (P > 0.1)." (PMID 29698474, 2018). "With the insertion of K1L and C7L, this response was tempered; infection with NYVAC-C-KC-ΔB8RΔB19R induced increased transcriptional levels of seven of the genes shown, relative to NYVAC-C-KC (IFI35, IFI44, IFI44L, IFIT1, IFIT3, IFITM1, and IFITM2)." (PMID 22096477, 2011). "The reduction in immune cell infiltration into the lungs of Ifi35-/- mice could be due to altered cytokine and chemokine responses following H5N1-VN/PR8 infection." (PMID 29698474, 2018). "Until recently, all functional studies on Ifi35 have been done in tissue culture models but its role and activity in vivo after infection with IAV or other pathogens is not well characterized." (PMID 29698474, 2018). "Similar to IFI35 and ISG15, it showed a consistent infection-induced transcriptional response." (PMID 28993767, 2017). "Additionally, histopathological assessment of lung consolidation in WT and Ifi35-/- mice at 5 dpi did not reveal significant differences in total lung area impacted by infection however, Ifi35-/- mice trended towards less total area of consolidation." (PMID 29698474, 2018). "Therefore, we hypothesized that IFN might be induced during early infection, as indicated by the subsequent enhanced production of ISGs because increased expression of a variety of ISGs, such as OSAL, MX1, IFIT5, ISG12-2, RSAD2, IFI35, protein kinase R (PKR), and IFI27L2, was found in this study." (PMID 24168272, 2013).
tumor (11 papers, 2012 to 2025). "In line with this, loss of IFI35 led to lower tumor number of CD8+ T cells." (PMID 37380972, 2023). "Future research should investigate whether drugs inhibiting growth factors such as IFI35 could cause tumor regression by inducing macroautophagy in these particular cells." (PMID 35740527, 2022). "Moreover, IFI35-overexpressing tumor cells caused slower tumor growth in both mouse models." (PMID 37380972, 2023). "In our study, we found that IFI35 promoted the secretion of tumor-derived CCL2, which led to the infiltration of MDSCs to promote TNBC immune escape." (PMID 38216673, 2024). "Collectively, it shows that IFI35 is highly expressed in TNBC tumor cells in response to IFN-γ stimulation." (PMID 38216673, 2024). "Similar to PD-L1, the mechanisms of IFI35 are hijacked by tumor cells, with IFI35 ultimately accelerating TNBC progression." (PMID 38216673, 2024). "Taken together, our results confirm that the IFI35 ablation and anti-PD-1 combination therapy obviously inhibited tumor growth and extended survival, suggesting a synergistic therapeutic effect." (PMID 38216673, 2024). "We observed that abrogation of IFI35 or anti-PD-1 treatment alone inhibited tumor growth in and prolonged overall survival of mice." (PMID 38216673, 2024). "It seems that IFI35 is a tumor suppressor, but its actual role in the tumor immune microenvironment (TIME) still remains to be demonstrated in animal models." (PMID 38216673, 2024). "In xenograft models, we found that IFI35 promoted TNBC immune escape in a tumor cell-intrinsic manner." (PMID 38216673, 2024). "As an interferon-stimulated gene (ISG), tumor-derived IFI35 was confirmed by us to promote MDSCs infiltration, and eventually lead to the dysfunction of CD8+T cells in TNBC." (PMID 38216673, 2024). "More importantly, we showed that IFI35 was secreted by tumor cells and promoted the proliferation and cytotoxicity of CD8+ T cells by activating the PI3K/AKT/mTOR signaling pathways." (PMID 37380972, 2023). "Tumor growth delay experiments were carried out using a murine anti-PD1 immune checkpoint inhibitor in syngeneic mice inoculated with IFI35-overexpressing CT26 cells." (PMID 37380972, 2023). "We next performed immunohistochemical staining of tumor tissue to examine the effect of IFI35 overexpression on the number of CD8+ T cells." (PMID 37380972, 2023). "Our study’s results demonstrate that the combination of anti-PD1 antibody treatment and IFI35 overexpression exhibited a synergistic effect in suppressing tumor growth." (PMID 37380972, 2023). "These in vitro and in vivo data suggested that the impact of IFI35 on tumor growth likely involves an immune-dependent mechanism." (PMID 37380972, 2023). "We found that immunocompetent mice inoculated with IFI35-overexpressing murine colon cells exhibited stronger anti-tumor ability than the controls." (PMID 37380972, 2023). "In summary, the tumor-secreted protein IFI35 plays crucial roles in the proliferation and cytotoxic activity of CD8+ T lymphocytes." (PMID 37380972, 2023). "Then, what role does IFI35 play in the local inflammatory microenvironment after tumor formation, pro-tumor or anti-tumor role, is worthy of our further study." (PMID 35844580, 2022). "Analysis of scRNA-seq TNBC data further supported the significant association between MUC1 and expression of IRDS genes encoding IRF7, BST2, IFI35 and IFITM1 in individual TNBC tumor cells." (PMID 35681561, 2022). "On day 45 after tumor cell inoculation, the suppression of tumor growth by IFI35 shRNA was significantly alleviated in the 3-MA-treated group compared with the control-treated group." (PMID 35740527, 2022). "Given the anti-tumor function of M1 macrophages and the better prognosis of patients with high IFI35 expression, it suggested that IFI35 plays a pro-inflammatory and anti-tumor role in the TIME." (PMID 35844580, 2022).